GTF2E1 (general transcription factor IIE subunit 1)
Description:
Recruits TFIIH to the initiation complex and stimulates the RNA polymerase II C-terminal domain kinase and DNA-dependent ATPase activities of TFIIH. Both TFIIH and TFIIE are required for promoter clearance by RNA polymerase.
Synonyms: TF2E1; TFIIE-A; FE
Tractability: Small molecule: a structure with a bound ligand is known. PROTAC: ubiquitination databases record sites on it; its protein half-life has been measured.
Gene: Protein-coding gene on chromosome 3 (120,742,370 to 120,783,368, forward strand). Ensembl gene ENSG00000153767.
Subcellular location: Nucleus
Subcellular location (Human Protein Atlas): Nucleoplasm
Pathways (Reactome):
Gene expression (Transcription): RNA Polymerase II Pre-transcription Events; RNA Polymerase II Promoter Escape; RNA Polymerase II Transcription Initiation; RNA Polymerase II Transcription Initiation And Promoter Clearance; RNA Polymerase II Transcription Pre-Initiation And Promoter Opening; RNA polymerase II transcribes snRNA genes
Disease: HIV Transcription Initiation; RNA Polymerase II HIV Promoter Escape; Transcription of the HIV genome
Gene Ontology:
Molecular function: protein binding; RNA polymerase II general transcription initiation factor activity
Biological process: RNA polymerase II preinitiation complex assembly; transcription by RNA polymerase II; transcription initiation at RNA polymerase II promoter
Cellular component: nucleoplasm; nucleus; transcription factor TFIID complex; transcription factor TFIIE complex
Genetic constraint (gnomAD): Loss-of-function variants: 12 observed, 33.34 expected, observed/expected ratio (o/e) 0.36, 90% interval 0.23 to 0.58. The upper end of that interval is the gene's LOEUF score, 0.58, which puts it in group 2 of 6, group 1 being the genes least tolerant of losing a copy. Missense variants: 457 observed, 576.47 expected, observed/expected ratio (o/e) 0.79, 90% interval 0.73 to 0.86. Synonymous variants: 186 observed, 202.6 expected, observed/expected ratio (o/e) 0.92, 90% interval 0.81 to 1.04.
Homologues: Orthologues: chimpanzee GTF2E1 (99% identical), macaque GTF2E1 (98% identical), dog GTF2E1 (96% identical), pig GTF2E1 (96% identical), rabbit GTF2E1 (95% identical), mouse Gtf2e1 (93% identical), rat Gtf2e1 (93% identical), guinea pig GTF2E1 (92% identical), tropical clawed frog gtf2e1 (76% identical), zebrafish gtf2e1 (72% identical), Drosophila melanogaster TfIIEalpha (43% identical), Caenorhabditis elegans gtf-2E1 (28% identical).
Diseases named in the same sentence as GTF2E1 in open-access papers:
GTF2E1 is named in the same sentence as 7 diseases in open-access papers, as found by Europe PMC text mining. Sharing a sentence is not in itself a finding about the gene and the disease. The quoted sentences say what the papers report.
atherosclerosis (1 paper, 2024). A disease characterized by the build-up of fatty material and calcium deposition in the arterial wall resulting in partial or complete occlusion of the arterial lumen. "The GTF2E1 knockdown group exhibited an altered expression of multiple genes, some of which are related to the development of atherosclerosis, colon carcinoma, and B-CLL." (PMID 39758846, 2024). "In summary, the whole gene expression in the GTF2E1 knockdown in HCT116 cells was analyzed using RNA-seq, revealing transcriptional changes in a series of genes involved in several aspects of atherosclerosis, colon cancer, and B-CLL." (PMID 39758846, 2024).
preeclampsia (1 paper, 2014). Preeclampsia is a hypertensive disorder of pregnancy that is characterized by new-onset hypertension with proteinuria presenting after 20 weeks of gestation, and depending on mild or severe forms may initially present with severe headache, visual disturbances, and hyperreflexia. "We also conducted an analysis of ENCODE Chip Seq data to infer common transcription regulatory networks of selected genes (such as TTD genes and GTF2E1) and gene regulators (such as EGFR, ATF3, and FLT1) implicated in preeclampsia." (PMID 24885447, 2014). "Analysis of gene expression patterns of placentas from a case-control study of preeclampsia using Algorithm for Reconstruction of Accurate Cellular Networks (ARACNE) revealed GTF2E1, a component of TFIIE which modulates TFIIH, among major regulators of differentially-expressed genes in preeclampsia." (PMID 24885447, 2014). "Our findings in HUVEC suggested the same downstream effects on the gene signature for GTF2E1 inhibition as that of FLT1 (i.e., a molecular mediator of preeclampsia symptoms) inhibition with the altered gene signature mimicking preeclampsia development." (PMID 24885447, 2014). "We analyzed the reactome database to identify proteins with direct and indirect (up to secondary) interactions with GTF2E1 and XPD in order to gain clues as to the cellular processes marking their involvement in preeclampsia." (PMID 24885447, 2014). "Our analyses of the reactome dataset identified direct interaction between GTF2E1 and XPD along with other proteins involved in transcription further pointing towards transcription mechanisms as relevant to preeclampsia." (PMID 24885447, 2014).
cancer (1 paper, 2019). A tumor composed of atypical neoplastic, often pleomorphic cells that invade other tissues. "Function enrichment analysis revealed that gene NDUFB4 and GTF2E1 affect cancer-related functions such as transmembrane transport and transformation factors." (PMID 31998369, 2019).
GTF2E1 also shares sentences with these, for which no sentence is quoted: colon carcinoma (1 paper); Obesity (1); retinal degeneration (1); trichothiodystrophy (1).